DPH1 (diphthamide biosynthesis 1)
Description:
Catalyzes the first step of diphthamide biosynthesis, a post-translational modification of histidine which occurs in elongation factor 2. DPH1 and DPH2 transfer a 3-amino-3-carboxypropyl (ACP) group from S-adenosyl-L-methionine (SAM) to a histidine residue, the reaction is assisted by a reduction system comprising DPH3 and a NADH-dependent reductase (By similarity). Acts as a tumor suppressor.
Synonyms: DPH2L; DPH2L1; OVCA1; DEDSSH
Tractability: PROTAC: ubiquitination databases record sites on it; its protein half-life has been measured.
Gene: Protein-coding gene on chromosome 17 (2,030,137 to 2,043,898, forward strand). Ensembl gene ENSG00000108963.
Subcellular location: Nucleus; Cytoplasm
Subcellular location (Human Protein Atlas): Nucleoplasm; Cell Junctions
Pathways (Reactome):
Metabolism of proteins: Synthesis of diphthamide-EEF2
Gene Ontology:
Molecular function: protein binding; 2-(3-amino-3-carboxypropyl)histidine synthase activity; 4 iron, 4 sulfur cluster binding
Biological process: protein histidyl modification to diphthamide
Cellular component: cytoplasm; nucleoplasm; nucleus; 2-(3-amino-3-carboxypropyl)histidine synthase complex; catalytic complex; cytosol; perinuclear region of cytoplasm; protein-containing complex
Genetic constraint (gnomAD): Loss-of-function variants: 59 observed, 55.46 expected, observed/expected ratio (o/e) 1.06, 90% interval 0.86 to 1.32. The upper end of that interval is the gene's LOEUF score, 1.32, which puts it in group 5 of 6, group 1 being the genes least tolerant of losing a copy. Missense variants: 628 observed, 598.81 expected, observed/expected ratio (o/e) 1.05, 90% interval 0.98 to 1.12. Synonymous variants: 238 observed, 240.09 expected, observed/expected ratio (o/e) 0.99, 90% interval 0.89 to 1.1.
Gene-disease validity (ClinGen):
ClinGen rates the evidence that DPH1 causes each of these diseases.
developmental delay with short stature, dysmorphic facial features, and sparse hair (autosomal recessive): Definitive.
Homologues: Orthologues: chimpanzee DPH1 (99% identical), macaque DPH1 (92% identical), pig DPH1 (91% identical), rabbit DPH1 (90% identical), guinea pig DPH1 (89% identical), mouse Dph1 (86% identical), rat Dph1 (82% identical), tropical clawed frog dph1 (66% identical), dog OVCA2 (61% identical), zebrafish dph1 (55% identical), Drosophila melanogaster Dph1 (55% identical), Caenorhabditis elegans dph-1 (50% identical). Paralogues in human: DPH2 (25% identical).
Diseases named in the same sentence as DPH1 in open-access papers:
DPH1 is named in the same sentence as 15 diseases in open-access papers, as found by Europe PMC text mining. Sharing a sentence is not in itself a finding about the gene and the disease. The quoted sentences say what the papers report.
ovarian carcinoma (8 papers, 2010 to 2024). A malignant neoplasm originating from the surface ovarian epithelium. "Examples of DPH gene alterations include gene copy number changes (loss of heterozygosity, LOH) of the DPH1 (OVCA1) gene in ovarian cancers or a deletion of the DPH7 (WDR85) gene." (PMID 28245596, 2017). "Togetherwith the association of mammalian DPH1/OVCA1 with ovarian cancer andneuronal development, this indicates that diphthamide modification plays an importantbiological role in higher eukaryal cells." (PMID 28357244, 2014). "Dph1 is a candidate tumor suppressor gene that has been cloned independently as Ovca1; a loss of Dph1 heterozygosity is frequent in breast and ovarian carcinoma and is associated to a decrease in protein expression." (PMID 21203470, 2010). "It has been found that approximately 80% of ovarian cancers have DPH1 gene deletions and that ELP3 is up-regulated in breast cancer cells, which in turn leads to increased levels of the oncoprotein DEK." (PMID 28555368, 2017). "So far, only one gene involved in diphthamide biosynthesis has been associated with human disease: diphthamide biosynthesis gene 1 (DPH1) was originally identified as tumor suppressor gene OVCA1 with frequent observations of loss of heterozygosity in various cancers, in particular ovarian cancer." (PMID 32576952, 2020). "Interestingly, compared to the pro-metastatic effect of Dph3, Dph1, which deletion in mouse leads to embryonic lethality as Dph3, was reported as a tumor suppressor gene for breast and ovarian cancer." (PMID 23185508, 2012). "LOH of the DPH1/OVCA1 gene has been described in cancer, in particular in ovarian cancer." (PMID 28245596, 2017).
developmental delay (2 papers, 2022 to 2025). "Homozygous or compound heterozygous variants of DPH1 have been reported in patients with developmental delays, unusual skull shape with or without craniosynostosis, sparse hair, and facial dysmorphisms." (PMID 36553485, 2022). "Loss-of-function (LoF) mutations in genes involved in diphthamide biosynthesis, such as DPH1, DPH2, and DPH5, result in developmental delay (DD), intellectual disability (ID), and multisystemic abnormalities." (PMID 40725455, 2025).
Intellectual disability (2 papers, 2020 to 2025). "Furthermore, a 2016 report described two siblings who also had intellectual disability and physical findings similar to those described with reduced function of DPH1 (short stature, prominent forehead, sparse hair, low-set ears)." (PMID 32576952, 2020). "Second, reduced functionality of DPH1, also acting in the first step of the diphthamide biosynthesis pathway, leads to similar phenotypes as the patient presented here, including intellectual disability, prominent forehead, short stature, cardiac defects, and other dysmorphic features." (PMID 32576952, 2020).
cleft palate (1 paper, 2024). Cleft palate is a fissure type embryopathy that affects the soft and hard palate to varying degrees.
liver disease (1 paper, 2025). "As shown in the heat map, male offspring exposed to HSD exhibited differential expression of ten genes associated with liver disease compared to normal offspring: Ager, Dph1, Steap4, Nfe2l1, Ppara, Rbmx, Nr1d1, Ccar2, Axl, and Abcg5." (PMID 41036197, 2025).
microcephaly (1 paper, 2020). A congenital or acquired developmental disorder in which the circumference of the head is smaller than normal for the person's age and sex. "Both macrocephaly and microcephaly have been described in individuals with variants in DPH1 and this patient also presented with abnormal head circumference (macrocephaly)." (PMID 32576952, 2020).
ovarian tumors (1 paper, 2012). "This notion is well supported by the fact that Dph1, also known as ovarian cancer-associated gene 1 protein (Ovca1), is a tumor suppressor gene that is frequently lost its heterozygosity in breast and ovarian tumors." (PMID 23185508, 2012).
tumor (11 papers, 1997 to 2024). "We have applied assays based on the recombinant complementation of DPH gene deficiency in tumor cells to address the functionality of DPH1 and DPH5 variants." (PMID 28245596, 2017). "MiR-218-5p is thought to be tumor suppressive and capable of negatively regulating DPH1 in CRC cells." (PMID 33997035, 2021). "DPH-1 is a tumor suppressor that is responsible for the first step of the unique protein modification that occurs on elongation factor 2 (eEF2), which converts a histidine residue to diphthamide." (PMID 23382692, 2013). "The reason why Dph1 and Dph3 function so differently in tumor cells needs to be further investigated." (PMID 23185508, 2012). "In addition, CDK3 and DPH1, which have been reported to inhibit or have the potential to inhibit tumor development, was observed to be markedly negatively correlated with risk scores." (PMID 34090418, 2021). "The phenotype of Dph4-null mutants is similar to Ovca1−/− mice but heterozygous mice for the Dph4 mutation do not develop tumors, suggesting an additional tumor suppressive function for Dph1." (PMID 21203470, 2010). "Key genes identified in this subtype included SLBP, MBD1, MINK1, DPH1, and CSNK1D, which are noted in existing literature for their roles in tumor malignancy and progression, thereby reinforcing the reliability of the ac4C score." (PMID 39648231, 2024).
cancer (8 papers, 2010 to 2024). A tumor composed of atypical neoplastic, often pleomorphic cells that invade other tissues. "Thus, variations or mutations that interfere with the functionality of the DPH1 may be biomarkers that associate with the response of cancer cells to targeted toxins that ADP-ribosylate the diphthamide on eEF2." (PMID 28245596, 2017). "Ovca1 heterozygote mice develop spontaneous cancer, thus, confirming the suppressor function of Dph1." (PMID 21203470, 2010). "In Dph1 heterozygous mice, cancer can spontaneously develop at 80–102 weeks of age." (PMID 23185508, 2012).
DPH1 also shares sentences with these, for which no sentence is quoted: breast carcinoma (1 paper); cervical cancer (1); craniosynostosis (1); diphtheria (1); glioblastoma (1); Miller-Dieker syndrome (1).